TRPM7 (transient receptor potential cation channel subfamily M member 7)
Diseases named in the same sentence as TRPM7 in open-access papers (continued):
Sharing a sentence is not in itself a finding about the gene and the disease.
ischemic cardiomyopathy (3 papers, 2017 to 2025). Ischemic cardiomyopathy is a cardiomyopathy in which a weakness in the muscle of the heart due to inadequate oxygen delivery to the myocardium with coronary artery disease being the most common cause. "The mechanism underlying the difference in TRPM7 current density between ischemic cardiomyopathy and control in the presence of extracellular divalents remains unclear, but has therefore to be related to the activity of the TRPM7 channels." (PMID 28129376, 2017). "Interestingly, in patients with ischemic cardiomyopathy, a direct relationship was shown between decreased TRPM7 expression in the left ventricle and decreased ejection fraction, i.e., a similar dysfunction was observed to that often observed with MG exposure." (PMID 40724903, 2025). "Because of the larger TRPM7 current in cardiac myocytes of patients with AF, especially those with ischemic cardiomyopathy, any pathophysiological regulation of these channels by factors such as acidosis could also be more marked in the diseased hearts." (PMID 28129376, 2017). "It would be interesting to test whether TRPM6 expression is upregulated in ischemic cardiomyopathy, since by contaminating TRPM7 measurements or by forming heteromeres with TRPM7 it could confer changes in sensitivity to modulators such as divalent cations and protons." (PMID 28129376, 2017). "A recent report also indicates that TRPM7 protein expression is not modified in tissues from ischemic cardiomyopathy despite a down-regulation of the corresponding genes." (PMID 28129376, 2017). "Given that the two cells presented above were from patients with and without history of myocardial ischemia, we examined whether ischemic cardiomyopathy has any influence on TRPM7 current amplitude." (PMID 28129376, 2017).
lung adenocarcinoma (3 papers, 2013 to 2020). A carcinoma that arises from the lung and is characterized by the presence of malignant glandular epithelial cells. "Analysis of our data revealed that compared with the null or weak TRPM7 expression in normal alveoli samples, TRPM7 was strongly expressed in lung adenocarcinoma or squamous cell lung carcinoma." (PMID 30477473, 2018). "It has also been shown that EGF can upregulate the surface expression of TRPM7 proteins and the amplitude of TRPM7 currents, which are important for the basal and the EGF-enhanced cell migration of human lung adenocarcinoma A549 cells." (PMID 23594099, 2013).
malignant glioma (3 papers, 2020 to 2023). A grade III or grade IV glioma arising from the central nervous system. "A large number of breast, lung, pancreatic, prostate, gastric, and head and neck cancers and malignant gliomas express high TRPM7 levels." (PMID 34458247, 2021). "For example, malignant glioma tissues express higher TRPM7 mRNA than normal brain tissues." (PMID 34458247, 2021). "Suppression of TRPM7 activity through the use of carvacrol and the use of TRPM7-siRNA dramatically reduced the proliferation, migration, and invasion levels of the U87MG malignant glioma cell line, which expresses higher levels of TRPM7 mRNA and protein than normal human astrocytes." (PMID 34458247, 2021).
metastatic tumors (3 papers, 2015 to 2020). "Other studies revealed higher TRPM7 and TRPM8 staining in metastatic tumors than in non-metastatic tumors, which was confirmed by qPCR for TRPM8." (PMID 33178018, 2020). "TRPM7 is also highly expressed in nasopharyngeal tumors, with higher TRPM7 mRNA levels in metastatic tumors than in primary tumors, and TRPM7 expression is absent in normal nasopharyngeal tissue." (PMID 31275168, 2019).
Nephropathy (3 papers, 2020 to 2023). A nonspecific term referring to disease or damage of the kidneys. "TRPM7 plays a pivotal role in the progression of nephropathy with kidney fibrosis, where it was shown that TRPM7 is upregulated during renal damage in a unilateral ureteral obstruction mouse model." (PMID 33291725, 2020). "While CBD was also protective in this nephropathy model, its effects on TRPM7 and SOCE23 were far less potent, indicating that alternative, yet to be determined mechanisms might underlie its protective effects." (PMID 37072467, 2023). "On the other hand, in cisplatin-induced nephropathy, CBGA mainly inhibited TRPM7 expression in tubular epithelial cells, and western blots therefore revealed a decrease in total TRPM7 protein in cisplatin-exposed mice treated with CBGA." (PMID 37072467, 2023). "In summary, CBGA has protective and anti-inflammatory effects in kidney damage likely through its inhibitory on TRPM7 and SOCE in the early stages of nephropathy and also suppresses renal fibrosis seen in chronic kidney disease model." (PMID 37072467, 2023).
renal fibrosis (3 papers, 2020 to 2023). A final common manifestation of a wide variety of chronic kidney diseases characterized by glomerulosclerosis and tubulointerstitial fibrosis. "Corroborating this, aldosterone-salt caused significant cardiac, vascular and renal fibrosis in WT mice, effects that were amplified in TRPM7+/Δkinase mice." (PMID 35882956, 2022). "Aldosterone-salt treatment exaggerated vascular dysfunction and amplified cardiovascular and renal fibrosis, with associated increased blood pressure in TRPM7+/Δkinase mice." (PMID 35882956, 2022). "Deficiency of the Mg2+-permeable channel/α-kinase TRPM7 in mice increases susceptibility to cardiovascular and renal fibrosis induced by aldosterone and salt." (PMID 35882956, 2022). "In summary, our data show that TRPM7 kinase deficiency, which is associated with hypomagnesemia and reduced intracellular Mg2+ concentration, increases susceptibility to cardiovascular and renal fibrosis induced by aldosterone and salt." (PMID 35882956, 2022). "In conclusion, our study defines TRPM7 kinase-regulated pathways and highlights a protective role for TRPM7-Mg2+ in cardiovascular and renal fibrosis induced by aldosterone." (PMID 35882956, 2022). "We conclude that pharmacological manipulation of TRPM7 using NS8593 interferes with Smad2/3 phosphorylation in renal fibrosis." (PMID 32047249, 2020). "The drug’s interference with the regulatory effect of TRPM7 on SOCE might therefore be a contributing factor in attenuating the progression of renal fibrosis." (PMID 32047249, 2020). "CBD also suppressed renal fibrosis, although it does not appear to have a strong effect of anti-inflammation in acute nephropathy, consistent with its rather poor efficacy in blocking TRPM7 or SOCE." (PMID 37072467, 2023).
squamous cell carcinoma (3 papers, 2018 to 2024). A carcinoma arising from squamous epithelial cells. "The silencing of TRPM7 suppressed several oncogenic signaling axes and reduced the migration, invasion, colony formation and tumorsphere formation of human squamous cell carcinoma cells in culture." (PMID 38255793, 2024). "Functional expression of TRPM7 channels has been demonstrated in a human hypopharingeal squamous cell carcinoma cell line." (PMID 38255793, 2024). "In addition, the fact that the blockade of TRPM7 or suppression of TRPM7 expression induced the inhibition of cancer cell growth and survival was verified in gastric, breast, and squamous cell carcinoma." (PMID 32168794, 2020).
status epilepticus (3 papers, 2020 to 2025). Status epilepticus is defined as a continuous seizure lasting more than 30 min, or two or more seizures without full recovery of consciousness between any of them. "Carvacrol treatment reduced recurrent status epilepticus (SE)-induced cell death in cornu Ammonis 1 (CA1) and hilus, possibly through its action on TRPM7 channels." (PMID 33114331, 2020). "To evaluate our hypothesis, we used two different TRPM7 inhibitors, carvacrol and 2-APB, using lithium-pilocarpine-induced status epilepticus (SE) as a model for TLE." (PMID 33114331, 2020).
acinar cell carcinoma (2 papers, 2015 to 2020). "In contrast to normal pancreatic acinar cells, which have no appreciable expression of TRPM7, there is moderate anti-TRPM7 immunoreactivity in all cases of acinar cell carcinoma examined." (PMID 25770184, 2015).
Alzheimer disease (2 papers, 2015 to 2019). A progressive, neurodegenerative disease characterized by loss of function and death of nerve cells in several areas of the brain leading to loss of cognitive function such as memory and language. "In addition, comparative gene expression analysis identified TRPM7 as one of the common upregulated genes in Alzheimer's disease and MS compared with healthy controls." (PMID 30453391, 2019). "In addition, TRPM7 is also involved in several neurodegenerative diseases such as western pacific amyotrophic lateral sclerosis (ALS), parkinsonism dementia (PD), and Alzheimer’s disease (AD)." (PMID 25799367, 2015).
Arrhythmia (2 papers, 2020 to 2025). Any cardiac rhythm other than the normal sinus rhythm. "In a similar fashion, a reduction in TRPM7 current may also predispose to cardiac arrhythmia." (PMID 31423533, 2020).
Arthritis (2 papers, 2018 to 2021). Inflammation of a joint. "In this study, we explored the influence of 2-APB on articular cartilage damage in an adjuvant-induced arthritis rat model and SNP-induced chondrocyte apoptosis, along with potential associations and mechanisms of action of TRPM7 and IHH." (PMID 33927631, 2021). "Our collective findings support an important role of TRPM7 in chondrocyte apoptosis and its potential utility as a therapeutic target for the arthritis with articular cartilage damage." (PMID 33927631, 2021). "In the CFA model of arthritis in rats, TRPM7 expression is upregulated in fibroblast-like synoviocytes." (PMID 30326593, 2018). "In summary, the current data suggests that agonism of TRPC5, TRPM3, TRPM8, and TRPV2 may help ameliorate or prevent arthritis, while antagonism of TRPM7 and TRPV4 may have a similar effect." (PMID 30326593, 2018). "2-APB contributes to cartilage protection in vivo by inhibiting the TRPM7 channel and IHH signaling and supports its potential therapeutic value in treatment of arthritis with articular cartilage damage." (PMID 33927631, 2021). "Blockage of TRPM7 with 2-APB relieved the clinical signs of AA in the rat model and reduced the arthritis score and paw swelling." (PMID 33927631, 2021). "One study demonstrated that TRPM7 silence could reduce the expression of IHH, while the relationship between TRPM7 and IHH and its roles in arthritis cartilage damage remains unclear." (PMID 33927631, 2021).
chronic myeloid leukemia (2 papers, 2025). "We did not observe any effect on the AKT expression in our models, although it has been shown that TRPM7 kinase regulates AKT signaling in chronic myeloid leukemia cells." (PMID 40274768, 2025). "In chronic myeloid leukemia (CML) cells, they showed that TRPM7 kinase regulates AKT and mothers against decapentaplegic homolog 2 (SMAD2) pathways leading to modulated cyclooxygenase-2 (COX-2) expression." (PMID 41395111, 2025).
colon adenocarcinoma (2 papers, 2017). "Our data confirm that waixA inhibits native TRPM7 currents in both normal primary mouse colon epithelial cells and HT-29 colon adenocarcinoma cells." (PMID 28810912, 2017).
colorectal adenoma (2 papers, 2022 to 2025). An adenoma that arises from the colon or rectum. "We previously reported that the Thr1482Ile functional variant (or G→A) in the TRPM7 was associated with significantly increased risks of both colorectal adenomas and serrated polyps in those with high Ca:Mg intake ratios." (PMID 40750038, 2025). "One of the first studies about the implication of TRPM7 in cancer progression informs on the association of an SNP TRPM7 polymorphism (Thr1482Ile) and an increased risk of developing hyperplastic polyps or colorectal adenoma, particularly in patients with a high Ca2+/Mg2+ intake diet." (PMID 36844925, 2022).
colorectal polyps (2 papers, 2025). "We previously reported that individuals with the transient receptor potential melastatin 7 (TRPM7) GA/AA genotype and consumed diets high in Ca:Mg ratio had increased risk of colorectal polyps." (PMID 40750038, 2025). "Our findings provide support for the TRPM7 genotype-Mg intake interaction affecting risk of colorectal polyp development." (PMID 40946805, 2025). "Our findings indicate that the gut microbiota in stool, rectal swab, and mucosa are associated with risk of metachronous colorectal polyps, and diet changes could modify the abundance of TRPM7-related microbes." (PMID 40750038, 2025). "The aim was to identify whether the gut microbiota plays a role in the association of TRPM7 genotype, Ca:Mg intake ratio, and risk of colorectal polyps." (PMID 40750038, 2025). "In general, these findings indicate that optimizing the Ca:Mg intake ratio through Mg supplementation may alter the microbiota linked to both the TRPM7 genotype and risk of metachronous colorectal polyps but not the host response biomarkers (necroptosis and inflammation)." (PMID 40750038, 2025).
congestive heart failure (2 papers, 2020 to 2023). Failure of the heart to pump a sufficient amount of blood to meet the needs of the body tissues, resulting in tissue congestion and edema. "Targeted cre-mediated knockdown of TRPM7 before E10 leads to congestive heart failure due to lack of myocardial compaction." (PMID 31423533, 2020).
deep vein thrombosis (2 papers, 2018 to 2020). "Further, we shed light on how the cellular signalling cascades involving TRPM7 channel and/or kinase activity culminate in pathologies as diverse as allergic hypersensitivity, arterial thrombosis and graft versus host disease (GVHD), stressing the need for TRPM7 specific pharmacological modulators." (PMID 30126133, 2018). "MiR-9 could promote migration, invasion, and angiogenesis of endothelial progenitor cells via downregulating transient receptor potential melastatin 7 (TRPM7) and activating PI3K/Akt/autophagy pathway, which might facilitate thrombi recanalization in deep vein thrombosis." (PMID 32850858, 2020).
ductal adenocarcinoma (2 papers, 2019 to 2023). "TRPM7 protein is also overexpressed in ductal adenocarcinoma compared to non-tumoral tissue, and TRPM7 levels are increased in invasive areas of Estrogen Receptor negative invasive ductal cancer." (PMID 31275168, 2019).
Glucose intolerance (2 papers, 2023). Glucose intolerance (GI) can be defined as dysglycemia that comprises both prediabetes and diabetes. "Here, we report that selective deletion of Trpm7 in β cells disrupted insulin secretion and led to progressive glucose intolerance." (PMID 36574297, 2023). "However, a latent induction of glucose intolerance was evident over 28 weeks, suggesting that TRPM7 disruption leads to progressive β cell dysfunction." (PMID 36574297, 2023).
head and neck squamous cell carcinoma (2 papers, 2022 to 2025). A squamous cell carcinoma that arises from any of the following anatomic sites: lip and oral cavity, nasal cavity, paranasal sinuses, pharynx, larynx, and salivary glands. "In head and neck squamous cell carcinoma (HNSCC), high TRPM7 expression correlates with invasiveness, cisplatin resistance, and poor prognosis." (PMID 40806720, 2025).
hyperaldosteronism (2 papers, 2020 to 2022). Overproduction of aldosterone by the adrenal glands, which may lead to hypokalemia and/or hypernatremia. "We identify TRPM7 downregulation and associated hypomagnesemia as putative molecular mechanisms underlying deleterious cardiovascular and renal effects of hyperaldosteronism." (PMID 35882956, 2022). "We identify TRPM7 downregulation as a putative mechanism underlying deleterious cardiovascular effects of hyperaldosteronism." (PMID 35882956, 2022). "Thus, high levels of aldosterone (hyperaldosteronism) alter the protein levels of TRPM7 expressed in the kidney, probably blocking the formation of the protein complex between TRPM6 and TRPM7, impacting on the reabsorption of Mg2+ at the distal tubule of nephrons and producing renal damage." (PMID 32471309, 2020).
insulinoma (2 papers, 2020 to 2023). "Inhibition of TRPM7 expression has been shown to protect against high glucose-induced neuron apoptosis, and knockdown of TRPM7 promotes significant insulin secretion in rat insulinoma INS-1 cells." (PMID 32393384, 2020).
magnesium deficiency (2 papers, 2022). A nutritional condition produced by a deficiency of magnesium in the diet, characterized by anorexia, nausea, vomiting, lethargy, and weakness. "Autophagy markers, β-catenin, and TRPM7 were assessed in vivo in the mouse cartilage, comparing between dietary magnesium deficiency and normal diet, by immunohistochemistry." (PMID 35804467, 2022). "The deletion of TRPM7 gene in cells was reported to result in intracellular magnesium deficiency." (PMID 35484564, 2022).
Migraine (2 papers, 2020 to 2022). "More studies are needed to better explore the potential role for these channels including TRPM7 in migraine pathophysiology." (PMID 33193064, 2020).
myocardial infarction (2 papers, 2022). Gross necrosis of the myocardium, as a result of interruption of the blood supply to the area, as in coronary thrombosis. "Similarly, the expression of TRPM7, assessed by mRNA and whole-cell currents in single cells, is upregulated post myocardial infarction in mouse cardiac fibroblasts." (PMID 36277180, 2022). "In addition, when expressed in cardiac fibroblasts, TRPM7 has profibrotic effects in cardiac disease conditions such as myocardial infarction, AF, and sick sinus syndrome." (PMID 36499188, 2022). "Such TRPM7-mediated profibrotic effects occur in cardiac disease conditions such as myocardial infarction, atrial fibrillation, and sick sinus syndrome as well as following receptor-mediated cardiac stimulation with agonists like angiotensin II and isoprenaline." (PMID 36277180, 2022).
myocardial ischemia (2 papers, 2017 to 2021). A disorder of cardiac function caused by insufficient blood flow to the muscle tissue of the heart. "An up-regulation of TRPM7 expression and its correlation with the severity of injury during myocardial ischemia/reperfusion have been shown in rat hearts." (PMID 28129376, 2017). "It is unlikely that the difference in TRPM7 current magnitude between atrial cardiomyocytes from patients with vs without history of myocardial ischemia can be explained by alterations in the TRPM7 biophysical properties." (PMID 28129376, 2017). "TRPM7 current density was higher in cardiomyocytes from patients with history of coronary vascular disease and the difference compared to cardiomyocytes from patients without history of myocardial ischemia increased with acidic pHo." (PMID 28129376, 2017).
nasopharyngeal tumors (2 papers, 2019 to 2023). "TRPM7 is also overexpressed in nasopharyngeal tumors, and elevated TRPM7 expression is associated with worse prognosis and metastasis." (PMID 36837670, 2023).
osteosarcoma (2 papers, 2012 to 2015). A usually aggressive malignant bone-forming mesenchymal neoplasm, predominantly affecting adolescents and young adults. "This screen determined that depletion of ADCK2, PRKAR2B, TRIB2 and TRPM7 most significantly downregulates nuclear accumulation of HIF-1α in response to the treatment of osteosarcoma cells." (PMID 22355351, 2012).
ovarian tumor (2 papers, 2022 to 2024). "Immunohistochemistry (IHC) displayed that carvacrol treatment reduced the expression of TRPM7 in xenograft ovarian tumor tissues in mice in SKOV3 cells in vitro." (PMID 35101076, 2022).
pancreatic adenosquamous carcinoma (2 papers, 2015 to 2020). A carcinoma that arises from the pancreas showing both ductal and squamous differentiation. "In pancreatic adenosquamous carcinoma and solid pseudopapillary neoplasm, TRPM7 is expressed at low to moderate levels." (PMID 25770184, 2015).